TRIM25 (tripartite motif containing 25)
Diseases named in the same sentence as TRIM25 in open-access papers (continued):
Sharing a sentence is not in itself a finding about the gene and the disease.
prostate carcinoma (continued). "TRIM25, also known as estrogen-responsive finger protein, is up-regulated in HCC, prostate cancer, and non-small-cell lung carcinoma." (PMID 32648571, 2020). "In PC TRIM25 is the E3 ubiquitin ligase of Ets related gene (ERG), an important transcription factor central for prostate cancers progression." (PMID 31137886, 2019). "TRIM25 as an ubiquitin ligase, targets ERG, mediating ERG polyubiquitination and stabilization in prostate cancer." (PMID 31137886, 2019). "Among them, TRIM25 has an oncogenic role in colorectal cancer (CRC), gastric cancer (GC) and prostate cancer (PC)." (PMID 31137886, 2019). "TRIM25 mRNA and protein expression was increased in ERG rearrangement-positive prostate cancer specimens, and we provide evidence that ERG upregulates TRIM25 expression." (PMID 27626314, 2016). "Notably, silencing of TRIM25 did not only diminish the cytoplasmic abundance of G3BP2 but also reduced total G3BP2 levels, suggesting a dual role of TRIM25 in both protein expression and subcellular localization of G3BP2 in prostate cancer cells." (PMID 39851496, 2025). "In the present study, we identified TRIM25 as an ubiquitin ligase that targets N-terminally truncated ERG in fusion-positive VCaP cells, and characterized its effects on ERG stability and its expression in prostate cancer." (PMID 27626314, 2016). "Finally TRIM19, TRIM25, and TRIM68, by regulating the activation of nuclear and hormone receptors, play a key role in the progression of leukaemia, as well as the development of breast and prostate cancer." (PMID 26077989, 2015). "Thus, the expression of TRIM25 in prostate cancer cells may not result in reduced ERG protein levels when USP9X is also expressed." (PMID 27626314, 2016).
gastric cancer (17 papers, 2017 to 2025). A primary or metastatic malignant neoplasm involving the stomach. "TRIM25 was under-expressed in human gastric cancer tissues, whose downregulation was associated with poor prognosis of patients." (PMID 39768197, 2024). "Studies have found that TRIM25 is associated with gastric cancer cell metastasis." (PMID 33858324, 2021). "LncRNA-NEAT1 reduces regulation of nuclear pre-mRNA domain containing 1B (RPRD1B) ubiquitination by blocking the interaction of RPRD1B with tripartite motif-containing 25 (TRIM25), promoting lymph node metastasis during the development of gastric cancer." (PMID 40296904, 2025). "This molecular competition impedes TRIM25-dependent K63-linked ubiquitination of HK2, thereby blocking its degradation and consequently promoting malignant proliferation in gastric cancer cells." (PMID 40796546, 2025). "A recent investigation has revealed that the expression of five genes linked to the cGAS-STING pathway, namely IFNB1, IFNA4, IL6, NFKB2, and TRIM25, exhibits potential as a valuable prognostic marker for OS in patients suffering from gastric cancer." (PMID 38240703, 2024). "Overexpression of TRIM25 in human gastric cancer cell lines (BGC823, SGC7901, and MGC803) reduced angiogenesis and MMP2 expression." (PMID 39768197, 2024). "For instance, TRIM25 is markedly overexpressed in gastric carcinoma, and TRIM25 knockdown suppresses the migration and invasion of gastric carcinoma cells via the TGF-β signal." (PMID 33506106, 2021). "It has also been reported that TRIM25 blockade by RNA interference inhibited migration and invasion of gastric cancer cells through transforming growth factor β (TGF-β) signaling." (PMID 28620119, 2017). "Previous studies have shown that TRIM25 promotes the progression of gastric cancer." (PMID 40796546, 2025). "Notably, genetic perturbation of TRIM25 (knockdown or overexpression) effectively rescued the NLRP12-mediated modulation of proliferative capacity in gastric carcinoma cells." (PMID 40796546, 2025). "TRIM25 was overexpressed in gastric cancer tissues and cell lines (MGC-803 and AGS)." (PMID 39768197, 2024). "TRIM25 promotes ubiquitination of Sp1 at K610 in gastric cancer." (PMID 37742010, 2023). "It has been reported that TRIM25 can promote the migration of gastric cancer cells." (PMID 28620119, 2017). "Mechanistically, NLRP12 binds to TRIM25 to prevent TRIM25 from participating in the K63-linked ubiquitination of HK2, which subsequently enhances the protein stability of HK2, thereby upregulating the expression of HK2 and promoting glycolysis in gastric cancer cells." (PMID 40796546, 2025). "For example, TRIM25 promotes SP1 ubiquitination at K610, further inhibiting the expression of MMP2 and angiogenesis in gastric cancer." (PMID 40796546, 2025). "JP3 (an antiangiogenic peptide) modulates the TRIM25/SP1/MMP2 axis to suppress tumor growth, metastasis, and angiogenesis in gastric cancer." (PMID 38955795, 2024). "TRIM25, a member of the TRIM family of proteins, is preferentially expressed in various human cancers, including breast, ovarian, lung, and gastric cancers." (PMID 38303029, 2024). "However, the TRIM25-mediated ubiquitination of HK2 has been less studied, especially in gastric cancer." (PMID 40796546, 2025). "TRIM25 inhibits MMP2 expression by mediating the ubiquitination at K610 and degradation of SP1, the transcription factor of MMP2, thereby suppressing angiogenesis in gastric cancer." (PMID 39768197, 2024). "TRIM25 and TRIM29 overexpression can both enhance the malignant degree of gastric cancer." (PMID 37628777, 2023). "In gastric cancer (GC), circNFATC3 binds to IGF2BP3 to enhance the stability of IGF2BP3 by suppressing TRIM25‐mediated ubiquitination, enhancing the IGF2BP3‐CCND1 regulatory axis and elevating CCND1 mRNA stability to promote the proliferation of GC cells." (PMID 39901896, 2025).
gastric cancer (continued). "Although the molecular mechanism governing the function of TRIM25 in colorectal cancer was not fully clear, it has been reported previously that TRIM25 positively regulates several cancer-related networks in gastric cancer, including migration, E-cadherin, and TGF-β pathways." (PMID 28620119, 2017).
liver cancer (12 papers, 2020 to 2026). An epithelial or non-epithelial malignant neoplasm that arises from the liver. "In vitro, TRIM25 silencing suppressed liver cancer cell proliferation and increased ferroptosis-related phenotypes, as indicated by increased ferrous iron and MDA levels, reduced GSH content and SOD activity, and elevated ROS and lipid peroxidation." (PMID 41993211, 2026). "The elevated TRIM21 and TRIM25 levels in liver cancer patients and the increased hazard ratio in patient groups with high TRIM21 and TRIM25 expression indicates the association of these TRIM proteins and vtRNA1-1 levels with tumor progression." (PMID 40096176, 2025). "Evidence shows that TRIM25 is low-expressed in many tumors, including liver cancer, lung cancer, and ovarian cancer, and is closely related to the poor prognosis of tumor patients." (PMID 41315221, 2025). "For example, in liver cancer, TRIM25 activates the Nrf2 signaling pathway and promotes tumor progression by interacting with and reducing the protein levels of Keap126." (PMID 33966039, 2021). "In vitro, liver cancer cell models with TRIM25 knockdown or overexpression were established." (PMID 41993211, 2026). "HBx also regulates the interaction between critical proteins, glucose‐regulated protein 78 (GRP78) and tripartite motif containing 25 (TRIM25) through ubiquitination, reducing TRIM25 ubiquitination levels, which increases SMAD family member 4 (SMAD4) activity and drives liver cancer progression." (PMID 40060195, 2025).
colorectal cancer (11 papers, 2017 to 2025). A primary or metastatic malignant neoplasm that affects the colon or rectum. "To identify TRIM25-associated pathways in colorectal cancer, we tested the connection between TRIM25 and TGF-β first, based on a recent report." (PMID 28620119, 2017). "If TRIM25 expression levels keep high in all tumor stages, we may use TRIM25 as a marker to detect patients with colorectal cancers and other TRIM25 associated cancers at a very early stage." (PMID 28620119, 2017). "TRIM25 is involved in the malignant progression of lung cancer and colorectal cancer by increasing the sensitivity of adriamycin-mediated chemotherapy." (PMID 41315221, 2025). "Consistently, TRIM25 is significantly upregulated in colorectal cancer tissues and different human colorectal cancer cell lines, thus implying a tumorigenic role of TRIM25 in these carcinomas." (PMID 31842382, 2019). "In the present study, we aim to investigate the function of TRIM25 in colorectal cancer in vitro and in vivo." (PMID 28620119, 2017). "To further verify TRIM25 expression in colorectal cancer, we then compared the TRIM25 expression levels between CRC lines and colonic epithelial cell line by real-time PCR." (PMID 28620119, 2017). "The results showed that TRIM25 was significantly overexpressed in colorectal cancer tissues, compared with the corresponding adjacent tissues." (PMID 28620119, 2017). "TRIM25 was found to be significantly up-regulated in colorectal cancer tissues and cancer cell lines through real-time PCR assay." (PMID 28620119, 2017). "In the present study, we found TRIM25 was significantly up-regulated in colorectal cancer tissues and cancer cell lines." (PMID 28620119, 2017). "In summary, our results indicate that TRIM25 also acts as an oncogene in colorectal cancer and it functions through TGF-β signaling pathway." (PMID 28620119, 2017). "To determine the function of TRIM25 in colorectal cancer, we first examined the expression levels of TRIM25 in human colorectal cancer samples and their corresponding adjacent tissues by real-time PCR." (PMID 28620119, 2017). "In conclusion, our results indicate TRIM25 acts as an oncogene in colorectal cancer and it activates TGF-β signaling pathway to promote tumor proliferation and metastasis." (PMID 28620119, 2017). "Colorectal cancer cells (CRCs) overexpressing TRIM25 exhibited a two-fold higher proliferation and migration rate compared with their parental lines in vitro." (PMID 28620119, 2017). "One of these proteins (TRIM25) is a member of the colorectal cancer signature." (PMID 36329531, 2022). "In addition, TRIM25 via induction of TGFβ signaling pathways promotes proliferation and invasion of colorectal cancer cells." (PMID 31842382, 2019). "Together, our study implicates that TRIM25-dependent inhibition of caspase-2 may represent a so far unrecognized survival mechanism of colorectal carcinoma cells." (PMID 31842382, 2019). "We need to evaluate the TRIM25 expression levels at different stages of colorectal cancers." (PMID 28620119, 2017). "Here, we investigated the function of TRIM25 in colorectal cancer." (PMID 28620119, 2017). "Since TRIM25 is not mutated in colorectal cancers, we should do further research to look for the upstream signaling pathway of TRIM25 in colorectal cancers, which stimulates TRIM25 overexpressing and results in the tumor progression." (PMID 28620119, 2017). "Functionally, the herein described TRIM25-dependent inhibition of caspase-2 could represent a so far unrecognized post-transcriptional survival mechanism utilized by colorectal carcinoma cells, and further supports the tumorigenic capacity of this particular TRIM member." (PMID 31842382, 2019). "Furthermore, our data implicate that inhibition of caspase-2 by TRIM25 protects tumor cells from chemotherapeutic drug-induced apoptosis and may constitute a novel mechanism of drug resistance in human colorectal carcinoma cells." (PMID 31842382, 2019).
colorectal cancer (continued). "Thus, TRIM25 represents potential targets for the treatment of colorectal cancer." (PMID 28620119, 2017). "For example, studies demonstrated that TRIM25 stabilizes EZH2, promoting oxaliplatin resistance in colorectal cancer cells." (PMID 41315221, 2025). "An RNA-specific binding of TRIM25 to caspase-2 mRNA in DLD-1 cells was validated by the RNP-IP RT-PCR assay and confirmed in the colorectal cancer cell line RKO." (PMID 31842382, 2019). "As our study showed, TRIM25 activates TGF-β signaling pathway to promote tumor proliferation and metastasis in colorectal cancer." (PMID 28620119, 2017). "In colorectal cancer, the oncogenic ubiquitin E3 ligase TRIM25 binds and stabilizes ATAD2 expression following genotoxic stress, which induces a positive ATAD2-E2F-TRIM25 feedback loop whereby ATAD2 acts as a transcriptional co-activator of E2Fs to promote TRIM25 expression." (PMID 38596293, 2024). "However, the expression of TRIM25 in colorectal cancer and the connection of TRIM25 and colorectal cancer metastases have not yet been investigated." (PMID 28620119, 2017). "However, the knowledge of the expression and possible role of TRIM25 in colorectal cancer is still lacking." (PMID 28620119, 2017).
lung carcinoma (11 papers, 2017 to 2025). "Recent research indicated that IGF2BP ubiquitination can be facilitated by circNDUFB2 as a scaffold to enhance the binding between TRIM25 and IGF2BPs in lung cancer." (PMID 35031058, 2022). "In particular, TRIM25 is overexpressed in breast, colorectal, and lung cancers, while PPARγ is downregulated in these cancers compared with normal tissues." (PMID 30323259, 2018). "In addition to elevating apoptosis sensitivity of lung cancer cells, the knockdown of TRIM25 markedly reduced other tumorigenic parameters, including proliferation and migration." (PMID 39851496, 2025). "Overexpression of TRIM25 in lung cancer can regulate tumor cell progression." (PMID 28620119, 2017).
non-small cell lung carcinoma (10 papers, 2020 to 2025). A group of at least three distinct histological types of lung cancer, including non-small cell squamous cell carcinoma, adenocarcinoma, and large cell carcinoma. "For example, circNDUFB2 functions as a scaffold to enhance the interaction between TRIM25 and IGF2BPs, thus facilitating the progression and metastasis of non-small cell lung cancer." (PMID 37407973, 2023). "For example, miR-365 restrains non-small cell lung carcinoma’s progress by suppressing TRIM25 expression." (PMID 33506106, 2021). "TRIM25 has been proven to be related to the differentiation degree, TNM staging, and lymph node metastasis of non-small cell lung cancer, and is related to the poor prognosis of patients." (PMID 41315221, 2025). "Tripartite motif containing 25 (TRIM25) can polyubiquitinate PTEN and activate the AKT/mTOR pathway in non-small cell lung cancer." (PMID 34805185, 2021).
glioma (8 papers, 2020 to 2025). A benign or malignant brain and spinal cord tumor that arises from glial cells (astrocytes, oligodendrocytes, ependymal cells). "To explore the biological significance of the interaction between Trim25 and ITPKB in glioma cells, we further examined cellular responses upon loss or gain of Trim25 function." (PMID 38438346, 2024). "Data of this study clearly indicated that activation of the NF-κB-PD-L1 axis by TRIM25 critically contributes to the immune repressive microenvironment of therapy-resistant glioma." (PMID 39851496, 2025). "In this type of cancer, high TRIM25 expression levels correlate with an unfavorable prognosis in patients with an aggressive subtype of glioma (WHO grade IV)." (PMID 39851496, 2025). "Like in HCC, TRIM25 propagates resistance of glioma to the chemotherapeutic drug temozolomide mainly through an inhibition of ferroptosis." (PMID 39851496, 2025). "In summary, TRIM25 expression was significantly higher in high-grade gliomas than in low-grade gliomas, suggesting that TRIM25 has potential as a prognostic marker in GBM." (PMID 38303029, 2024). "Kaplan–Meier survival analysis revealed that patients with glioma expressing high levels of TRIM25 exhibited worse overall survival (OS) compared to patients with lower TRIM25 expression levels." (PMID 38303029, 2024). "For example, tripartite motif-containing 25 (TRIM25) facilitates immunosuppression and inhibits glioma apoptosis via activating NF-κB." (PMID 39353894, 2024). "Western blotting analysis of lysates from 19 primary tumors (WHO grades II-IV) and 4 NBT samples further confirmed the upregulation of TRIM25 in human gliomas." (PMID 38303029, 2024). "TRIM25 expression was significantly higher in high-grade gliomas than in low-grade gliomas, while expression was minimal in NBT samples." (PMID 38303029, 2024). "In contrast, ITPKB stability was significantly attenuated in glioma cells with Trim25 overexpression." (PMID 38438346, 2024). "To determine whether protein levels were altered, we used IHC to assess TRIM25 protein expression levels in primary glioma samples and NBT samples." (PMID 38303029, 2024). "In this study, we found that TRIM25 is upregulated in glioma and promotes tumor growth." (PMID 38303029, 2024). "Immunoprecipitation assays using a Trim25 antibody confirmed the interaction between Trim25 and endogenous ITPKB in glioma cells, with a weaker interaction observed in resistant cell lines compared to sensitive cells." (PMID 38438346, 2024). "To investigate the role of TRIM25 in GBM, we knocked down TRIM25 expression in LN229 and U251 human glioma cells using two different siRNAs." (PMID 38303029, 2024). "Difference in TRIM25 expression levels between nonneoplastic brain tissue samples and primary glioma samples was demonstrated using publicly available glioblastoma database, immunohistochemistry, and western blotting." (PMID 38303029, 2024).
influenza (7 papers, 2014 to 2025). An acute viral infection of the respiratory tract, occurring in isolated cases, in epidemics, or in pandemics; it is caused by serologically different strains of viruses (influenzaviruses) designated A, B, and C, has a 3-day incubation period, and usually lasts for 3 to 10 days. "Future work will benefit from examining ZAP, KHNYN, and TRIM25 susceptibility of many influenza strains derived from humans, wild birds, agricultural poultry, and domestic mammals as well as emerging mammalian H5N1 IAV isolates." (PMID 39763980, 2025). "The conservation of a RIG-I splice variant present in tissue samples of influenza-infected ducks provides indirect evidence of the importance of the TRIM25 RIG-I physical interaction, and indicates the same region of duck RIG-I is involved." (PMID 24466302, 2014). "In summary, TRIM25 plays a vital role in the host response to Influenza infection in mammals, and is actively modulated by Orthomixoviruses." (PMID 33985436, 2021). "Considering the crucial role of the NS1 interactions with PI3K and TRIM25 on influenza infection and pathogenesis and the fact that the interaction surfaces of NS1 with both proteins overlap, in the current work, we explored the potential of these two PPIs to be targets of new antiviral agents." (PMID 36769298, 2023). "NS1 interaction with TRIM25 also plays an essential role in influenza infection and pathogenesis." (PMID 36769298, 2023). "TRIM25 regulates the RIG-I-mediated IFN pathway, leading to antiviral response to influenza and other RNA viruses." (PMID 35440123, 2022).